DHRS3 (dehydrogenase/reductase 3)
Diseases named in the same sentence as DHRS3 in open-access papers:
DHRS3 is named in the same sentence as 34 diseases in open-access papers, as found by Europe PMC text mining. Sharing a sentence is not in itself a finding about the gene and the disease. The quoted sentences say what the papers report.
neuroblastoma (6 papers, 2008 to 2021). Neuroblastoma (NB) is the most common solid, extracranial childhood tumor. "Although DHRS3 was found to be upregulated in papillary thyroid cancer and neuroblasts, DHRS3 was negatively correlated with the metastasis of papillary thyroid carcinoma and was associated with better prognosis of neuroblastoma." (PMID 34830998, 2021). "Association between retSDR1/DHRS3 and neuroblastoma has been reported." (PMID 27879662, 2016). "Some studies have found monoallelic deletion of DHRS3 in some neuroblastoma cell lines, but others have shown that DHRS3 is constitutively expressed in breast cancer cell lines and highly expressed in papillary thyroid carcinoma." (PMID 33553182, 2021). "DHRS3, which is frequently deleted or rearranged in neuroblastomas, is critical for the generation of a storage form of retinol." (PMID 33553182, 2021). "DHRS3 is an enzyme strongly induced by RA in human neuroblastoma and leukemic monocyte cell lines, which mainly catalyzes the reduction of all-trans-retinal, an opposite reaction of RA formation." (PMID 33902658, 2021). "We present eight genes (KRT19, PRKCDBP, SCNN1A, POU2F2, TGFBI, COL1A2, DHRS3 and DUSP23) that are methylated in neuroblastoma, most of them not previously reported as such, some of which also distinguish between biological subsets of neuroblastoma tumors." (PMID 21314941, 2011).
papillary thyroid carcinoma (6 papers, 2013 to 2022). "Although DHRS3 was found to be up-regulated in papillary thyroid cancer and neuroblasts, DHRS3 was negatively correlated with the metastasis of papillary thyroid carcinoma and was associated with a better prognosis for NB." (PMID 36231133, 2022). "Dhrs3 is expressed in multiple differentiated tissues besides the retina, and DHRS3 expression has been found to be upregulated in human papillary thyroid carcinomas, although it is negatively correlated with subsequent lymph node metastasis." (PMID 23179634, 2013). "As it has been noted on previous work: CST6, CXCL14, DHRS3, and SPP1 are regulated by BRAF signaling and may play a role in papillary thyroid carcinoma pathogenesis." (PMID 25887408, 2015).
breast carcinoma (4 papers, 2015 to 2021). "DHRS3 is potently induced by retinoic acid, an antiproliferative vitamin-A derivative so alcohol may interact with vitamin-A associated pathways in breast cancer cell lines." (PMID 26661278, 2015). "It is found that DHRS3 is down-regulated in breast cancer and breast cancer brain metastases." (PMID 30918839, 2019). "Dehydrogenase/reductase member 3 (DHRS3) is involved in tumor suppression pathways and is constitutively expressed in breast cancer cell lines." (PMID 33193731, 2020). "Among which, IBSP, MMP9, TNFAIP6, DHRS3, RIPK4, and CD200 had a diagnose value for patients with breast cancer bone metastasis." (PMID 30918839, 2019). "Dehydrogenase/reductase 3 (DHRS3) has been found to be involved in the tumor suppressive pathway and constitutively expressed in breast cancer cell lines." (PMID 30918839, 2019). "The research of TNFAIP6, DHRS3, ASS1, RIPK4, VIM, and CD200 in breast cancer may indicate that those genes may play a crucial role in the development of breast cancer bone metastasis." (PMID 30918839, 2019). "Besides some published potential biomarkers of breast cancer bone metastasis were identified in our study, we also detected some novel biomarkers or their relationship with breast cancer bone metastasis has never been reported, such as TNFAIP6, DHRS3, ASS1, RIPK4, VIM, CD200." (PMID 30918839, 2019).
gastric cancer (4 papers, 2021 to 2025). A primary or metastatic malignant neoplasm involving the stomach. "Moreover, CYP26B1 and DHRS3 up-regulation indicates that ATRA causes significant effects on the metabolism of endogenous vitamin-A in gastric-cancer cells." (PMID 37951921, 2023). "Our study explored the role of DHRS3 in gastric cancer (GC) and its clinicopathological significance and associated mechanisms." (PMID 33553182, 2021). "Reduced expression of DHRS3 has been previously shown in gastric cancer, and its ectopic expression was found to inhibit cell proliferation and migration." (PMID 40022152, 2025). "This suggests that DHRS3 is likely to require other gene-products/factors or pathways, which are selectively stimulated/repressed by the retinoid only in sensitive gastric cancer cells, to play a role in the anti-proliferative action of ATRA." (PMID 37951921, 2023). "Thus, IRF1 up-regulation may be responsible for the increase in DHRS3 that ATRA triggers in gastric-cancer cells." (PMID 37951921, 2023). "A final and significant outcome of our study is the identification of a restricted number of genes which are up-regulated (IRF1, CTSS, PSMB10, CYP26B1, DHRS3 and TINAGL1) and down-regulated (AHNAK2) by ATRA in all the retinoid-sensitive gastric-cancer cell-lines considered." (PMID 37951921, 2023). "These last data indicate that also DHRS3 up-regulation may be involved, at least partially, in the growth-inhibitory effects exerted by ATRA in gastric-cancer cells." (PMID 37951921, 2023). "Dhrs3 and Rarb have been correlated with various types of cancer, including CRC and gastric cancer." (PMID 35457963, 2022). "However, it must be pointed out that the RNA-sequencing data indicate that ATRA induces DHRS3 expression in all the gastric cancer cell-lines considered, regardless of their relative sensitivity/resistance to the retinoid." (PMID 37951921, 2023).
craniosynostosis (2 papers, 2023 to 2025). Craniosynostosis is defined as the premature fusion of one or more cranial sutures leading to secondary distortion of skull shape resulting in skull deformities with a variable presentation. "Collectively, these observations further support a pathophysiological mechanism by which variants in DHRS3 perturb retinoid metabolism and RA signaling, which results in craniosynostosis." (PMID 40519748, 2025). "The first, a homozygous 3.9 kb deletion encompassing the promoter and 5′-UTR of DHRS3, was identified in two siblings from a consanguineous Pakistani family with craniosynostosis." (PMID 37946251, 2023). "Here, we have extended these parallels by demonstrating that Dhrs3−/− mouse embryos exhibit axial skeletal anomalies involving cervical vertebral fusion and cranial skeletal anomalies that affect parietal bone ossification, with narrower coronal sutures and the onset of craniosynostosis." (PMID 40519748, 2025).
glioma (2 papers, 2008 to 2024). A benign or malignant brain and spinal cord tumor that arises from glial cells (astrocytes, oligodendrocytes, ependymal cells). "ADH4, DHRS3, LRAT, RDH10, RDH12, and RDH5 were higher expressed in the high-glioma-risk group while DHRS9 was lower expressed." (PMID 39465792, 2024). "After that, we found that 6 immune checkpoints (CD274, CTLA4, LAG3, LGALS9, PDCD1, and PDCD1LG2) were significantly upregulated in the high-glioma-risk group, while RDH5, RDH10 and DHRS3 simultaneously have a substantial positive connection with PDCD1LG2." (PMID 39465792, 2024). "Ultimately, ADH4, DHRS3, DHRS9, LRAT, RDH10, RDH12, and RDH5 were selected as prognostic genes for building an RA metabolism–related prognostic signature with glioma." (PMID 39465792, 2024). "We identified 7 promising prognostic genes (ADH4, DHRS3, DHRS9, LRAT, RDH10, RDH12, and RDH5) within glioma and developed a prognostic model with significant predictive accuracy." (PMID 39465792, 2024). "The prognostic signature comprised of ADH4, DHRS3, DHRS9, LRAT, RDH10, RDH12, and RDH5 based on RA metabolism was established, which provided a theoretical basis and reference value for the research of glioma." (PMID 39465792, 2024).
atherosclerosis (1 paper, 2021). A disease characterized by the build-up of fatty material and calcium deposition in the arterial wall resulting in partial or complete occlusion of the arterial lumen. "For example, it has been reported that retinoic acid (RA) reduces plaque formation in an atherosclerosis prone mouse model, and here, we observed an upregulation of RA receptors (RARB) and two RA receptor responsive genes (DHRS3 and RARRES1) following abrogation of AMPA receptor signaling." (PMID 33959644, 2021).
central nervous system infection (1 paper, 2024). "We observed attenuated disease development in mice with DHRS3 knockdown, as shown by disease scores reflecting central nervous system infection." (PMID 38989466, 2024).
gastric tumor (1 paper, 2021). "To extend this observation, we treated gastric tumor cells (SGC7901, AGS, MKN45, and MKN28) with a demethylating agent (5′-Aza) and quantified the DHRS3 mRNA." (PMID 33553182, 2021). "We demonstrated that the protein expression of DHRS3 was downregulated in a large percentage of gastric tumor specimens compared with corresponding non-tumor tissues." (PMID 33553182, 2021).
liposarcoma (1 paper, 2007). A usually painless malignant tumor that arises from adipose tissue. "In addition, genes involved in receptor activity, signaling and lipid metabolism (some of which have previously been reported in liposarcoma) such as ACAA2, ARSA, DHRS3, PDE3A, and PPARA, were upregulated." (PMID 17359542, 2007).
lung disease (1 paper, 2022). "The neighboring genes showing association of expression with DNAm at the identified CpGs included TRAM1, which has been shown to be correlated with FEV1, and DHRS3 whose expression is associated with smoke exposure, a strong risk factor for lung disease." (PMID 35906571, 2022).
orofacial cleft (1 paper, 2022). A disorder of facial skeleton that is characterized by cleft lip and/or cleft palate that result in feeding, speech and hearing problems caused by failures during development. "Mouse knockouts of Acan,Dhrs3, Kmt2d, Recql4, Shh and Tp63 showed orofacial cleft phenotypes." (PMID 35817949, 2022).
prostate carcinoma (1 paper, 2023). A carcinoma that arises from epithelial cells of the prostate gland. "circDHRS3, with a length of 359 bp sourced from (Sanger) sequencing using the unique back-splicing site of circDHRS3 as opposed to DHRS3, appeared to be downregulated in prostate cancer of high Gleason grade." (PMID 36840946, 2023).
retinal diseases (1 paper, 2016). "retSDR1/DHRS3 has not been associated with any retinal diseases in humans." (PMID 27879662, 2016).
rheumatoid arthritis (1 paper, 2021). A chronic, systemic autoimmune disorder characterized by inflammation in the synovial membranes and articular surfaces. "In a study of rheumatoid arthritis (RA), DHRS3 was detected as one candidate genes for RA, as its expression was twice as high in the RA case group as in the control group." (PMID 33691763, 2021).
sarcoma (1 paper, 2022). A usually aggressive malignant neoplasm of the soft tissue or bone. "Notably, in a sarcoma study, it was found that a four-gene signature, including DHRS3, JRK, TARDBP, and TTC3, can predict patient survival based on a real-world cohort." (PMID 36231133, 2022).
viral infection (1 paper, 2024). "Because we observed that RA was declined in response to viral infection, these data indicated that viral infection prevented RA synthesis through upregulation of DHRS3." (PMID 38989466, 2024). "Unexpectedly, Dhrs3 transcription was upregulated by viral infection." (PMID 38989466, 2024).
tumor (16 papers, 2013 to 2026). "Reduced expression of DHRS3 is implicated in gastric carcinogenesis, which suggests DHRS3 is a tumor suppressor." (PMID 33553182, 2021). "We further revealed that the anti-tumor action of RARαS77A was, at least in part, mediated by the up-regulation of miR-3074-5p, which directly targeted DHRS3, a reductase negatively associated with TNBC patient survival." (PMID 33902658, 2021). "A recent study found that DHRS3 was hypermethylated and downregulated in GC patients and reduced expression of DHRS3 is implicated in gastric carcinogenesis, which suggested DHRS3 could be a tumor suppressor." (PMID 36193316, 2022). "Dhrs3 is under investigation as a candidate for shared identity with Gct1, as we continue to examine all candidate genes in the interval using a whole-locus customized sequencing approach, gene expression analysis, and in vivo functional strategies in GC tumor-susceptible SWR mice." (PMID 23179634, 2013). "Another potential tumor suppressor gene is the Dhrs3 gene, which together with Rarb was modulated in pathways relating to retinol metabolism." (PMID 35457963, 2022). "Dhrs3 as a tumor suppressor gene has been suggested to play a critical role in connecting the retinol metabolism with the circadian rhythm, leading to an alteration of immune responses and cellular metabolism." (PMID 35457963, 2022). "Ectopic expression of DHRS3 in GC cells inhibited cell proliferation and migration in vitro, decreased tumor growth in vivo." (PMID 33553182, 2021). "We found that DHRS3 mRNA levels were significantly lower in tumor tissues than in normal tissues (P < 0.05), supporting the notion that DNA methylation of the DHRS3 gene promoter correlates inversely with the expression of the gene." (PMID 33553182, 2021). "The distinct expression status of DHRS3 among different tumor types needs further investigation to gain an understanding of the physiological function of the gene during tumorigenesis." (PMID 33553182, 2021). "In this study, we analyzed the majority of the cases by Mass-Array and found that DHRS3 promoter methylation was tumor specific (P < 0.01)." (PMID 33553182, 2021). "To further study the supposed tumor suppressor function of DHRS3 in GC, we performed both in vitro and in vivo assays." (PMID 33553182, 2021). "Taken together, these findings indicate that miR-3074-5p mediated (at least in part) the tumor-suppressive effect of RARαS77A by targeting DHRS3 in TNBC." (PMID 33902658, 2021). "Additionally, comparable to hypermethylation of RASSF1, hypermethylation of TMEM240 and DHRS3 have been described in several types of cancers, and these genes have been proposed as tumour suppressor genes." (PMID 39589853, 2025). "To further investigate the tumor suppressive effect of DHRS3 in GC cells, we investigated whether DHRS3 could suppress the growth of GC cells in nude mice." (PMID 33553182, 2021). "We found different methylation patterns of the DHRS3 promoter between the tumor and normal tissues." (PMID 33553182, 2021). "Our results suggest that the inhibition of RARαS77 phosphorylation by either expressing RARαS77A or inhibiting RARα’s phosphokinase CDK7, can bypass RA stimuli to transactivate tumor-suppressive miR-3074-5p and reduce oncogenic DHRS3, thus overcoming the RA-resistance of TNBC." (PMID 33902658, 2021). "Thus, the inactivation of DHRS3 by methylation of the promoter would favor tumor progression and lead to a worse outcome for patients." (PMID 33553182, 2021). "Taken together, it is implied that DHRS3 plays the role of a tumor suppressor in GC." (PMID 33553182, 2021). "DHRS3 promoters in tumor samples were generally hypermethylated." (PMID 33553182, 2021).
tumor (continued). "The silencing of DHRS3 in primary GC cells suggests that DHRS3 may function as a tumor suppressor." (PMID 33553182, 2021). "This anti-tumor action of THZ1 may be attributed to the down-regulation of DHRS3." (PMID 33902658, 2021). "Therefore, by overexpressing DHRS3 in cells with hypo-phosphorylated RARαS77, we sought to investigate whether DHRS3 might offset the anti-tumor action of RARαS77A." (PMID 33902658, 2021). "Re-expression of DHRS3 significantly inhibited both growth and clone formation of cultured MKN28 cells and reduced tumor size in nude mice." (PMID 33553182, 2021). "Of these, DHRS3, DUSP4, GAN, RGS12, and TRIM14 are known oncogenes or tumor suppressors (as indicated by CancerMine)." (PMID 33849068, 2021). "We also investigated DHRS3 expression in normal breast, primary, and metastatic TNBC to correlate their levels with tumor progression." (PMID 30486871, 2018). "We analyzed the methylation status of DHRS3 in more detail in 100 primary tumor tissues and corresponding non-tumor tissues from 50 patients with GC by Mass-Array." (PMID 33553182, 2021). "We show here that RARαS77 hyper-phosphorylation contributes to RA-resistance and tumor progression of TNBC by transcriptional suppression of miR-3074-5p, thus suggesting the RARα/miR-3074-5p/DHRS3 axis may serve as novel therapeutic targets for TNBC." (PMID 33902658, 2021). "The negative correlation between the methylation status of DHRS3, LRAT, and RDH10 and their gene expression levels suggests that methylation changes could regulate the expression of key genes involved in RA metabolism, possibly altering tumor behavior." (PMID 40535799, 2025).
cancer (6 papers, 2021 to 2026). A tumor composed of atypical neoplastic, often pleomorphic cells that invade other tissues. "In an attempt to assess the prognosis of GC patients based on the methylation levels of DHRS3 after surgery, we further analyzed the Mass-Array data and found that composite CpG sites 9 and CpG 10 were associated with an increased risk of cancer-related death." (PMID 33553182, 2021). "Deletion of DHRS3 results in loss of local retinol storage, leading to shortage of vitamin A active metabolites and thus contributing to cancer development and progression." (PMID 33553182, 2021). "Short-chain dehydrogenase/reductase 3, DHRS3, a retinol-metabolizing enzyme, exhibits paradoxical roles across cancers, but its specific function in HCC is poorly understood." (PMID 42142584, 2026). "The GENT database indicates that DHRS3 mRNA is down-regulated in cancers of the bladder, lung, ovary, skin, stomach, and vagina compared with corresponding normal tissues, but is upregulated in cancers of the brain, cervix, and uterus." (PMID 33553182, 2021). "Further study has elucidated that deletion of DHRS3 might contribute to cancer development and progression by reducing the production of vitamin A." (PMID 33553182, 2021). "Several studies have already discovered differential gene expression in cancer cell-lines based on global gene expression analysis, such as CYP26B1, DHRS3, and TINAGL1 were up-regulated by ATRA." (PMID 39210795, 2025).
DHRS3 also shares sentences with these, for which no sentence is quoted: hepatocellular carcinoma (2 papers); lung carcinoma (2); bone metastasis (1); congenital heart disease (1); glioblastoma (1); Intellectual disability (1); ischemic stroke (1); kidney stone (1); melanoma (1); Parkinson (1); scoliosis (1); Stillbirth (1); thyroid (1); triple-negative breast carcinoma (1); tumors of the ovary (1).